MMP3 (matrix metallopeptidase 3)
Description:
Metalloproteinase with a rather broad substrate specificity that can degrade fibronectin, laminin, gelatins of type I, III, IV, and V; collagens III, IV, X, and IX, and cartilage proteoglycans. Activates different molecules including growth factors, plasminogen or other matrix metalloproteinases such as MMP9. Once released into the extracellular matrix (ECM), the inactive pro-enzyme is activated by the plasmin cascade signaling pathway. Also acts intracellularly. For example, in dopaminergic neurons, gets activated by the serine protease HTRA2 upon stress and plays a pivotal role in DA neuronal degeneration by mediating microglial activation and alpha-synuclein/SNCA cleavage. In addition, plays a role in immune response and possesses antiviral activity against various viruses such as vesicular stomatitis virus, influenza A virus (H1N1) and human herpes virus 1. Mechanistically, translocates from the cytoplasm into the cell nucleus upon virus infection to influence NF-kappa-B activities.
Synonyms: SL-1; MMP-3; STMY1; CHDS6; STMY; STR1
Tractability: Small molecule: a drug acting on it is in phase 2 or 3 trials; a structure with a bound ligand is known; a high-quality ligand is known; it has a high-quality binding pocket; it belongs to a druggable protein family. Antibody: its Gene Ontology location is reachable by antibodies, with high confidence; UniProt places it where antibodies can reach, with medium confidence; UniProt predicts a signal peptide or a membrane-spanning region. PROTAC: ubiquitination databases record sites on it; a small molecule that binds it is known.
Target class: Metallo protease; Metallo protease M10A subfamily; Metallo protease MAM clan; Protease; Enzyme
Gene: Protein-coding gene on chromosome 11 (102,835,801 to 102,843,609, reverse strand). Ensembl gene ENSG00000149968.
Subcellular location: Secreted, extracellular space, extracellular matrix; Nucleus; Cytoplasm
Subcellular location (Human Protein Atlas): Vesicles; Predicted to be secreted
Pathways (Reactome):
Extracellular matrix organization: Activation of Matrix Metalloproteinases; Assembly of collagen fibrils and other multimeric structures; Collagen degradation; Degradation of the extracellular matrix
Signal Transduction: EGFR Transactivation by Gastrin; Extra-nuclear estrogen signaling
Immune System: Interleukin-4 and Interleukin-13 signaling
Gene Ontology:
Molecular function: endopeptidase activity; metalloendopeptidase activity; metallopeptidase activity; peptidase activity; protein binding; serine-type endopeptidase activity; zinc ion binding
Biological process: cellular response to UV-A; negative regulation of reactive oxygen species metabolic process; positive regulation of protein-containing complex assembly; proteolysis; cellular response to lipopolysaccharide; cellular response to nitric oxide; cellular response to reactive oxygen species; collagen catabolic process; extracellular matrix disassembly; extracellular matrix organization; regulation of neuroinflammatory response; response to amyloid-beta; negative regulation of phosphatidylinositol 3-kinase/protein kinase B signal transduction; protein catabolic process
Cellular component: cytoplasm; nucleus; extracellular region; cytosol; extracellular matrix; mitochondrion
Genetic constraint (gnomAD): Loss-of-function variants: 46 observed, 46.61 expected, observed/expected ratio (o/e) 0.99, 90% interval 0.78 to 1.26. The upper end of that interval is the gene's LOEUF score, 1.26, which puts it in group 5 of 6, group 1 being the genes least tolerant of losing a copy. Missense variants: 547 observed, 579.01 expected, observed/expected ratio (o/e) 0.94, 90% interval 0.88 to 1.01. Synonymous variants: 216 observed, 214.57 expected, observed/expected ratio (o/e) 1.01, 90% interval 0.9 to 1.13.
Homologues: Orthologues: chimpanzee MMP3 (99% identical), macaque MMP3 (95% identical), rabbit MMP3 (84% identical), dog MMP3 (81% identical), pig MMP3 (81% identical), mouse Mmp3 (77% identical), guinea pig MMP3 (77% identical), rat Mmp3 (75% identical), zebrafish mmp13b (49% identical), zebrafish mmp30 (44% identical), zebrafish mmp25b (37% identical), Drosophila melanogaster Mmp1 (34% identical), and 10 more. Paralogues in human: MMP10 (78% identical), MMP1 (53% identical), MMP12 (51% identical), MMP8 (51% identical), MMP27 (50% identical), MMP13 (49% identical), MMP20 (45% identical), MMP2 (44% identical), MMP14 (40% identical), MMP15 (40% identical), MMP9 (39% identical), MMP24 (39% identical), and 11 more.
Diseases named in the same sentence as MMP3 in open-access papers:
MMP3 is named in the same sentence as 508 diseases in open-access papers, as found by Europe PMC text mining. Sharing a sentence is not in itself a finding about the gene and the disease. The quoted sentences say what the papers report.
breast cancer (153 papers, 2004 to 2026). A primary or metastatic malignant neoplasm involving the breast. "Results showed that MMP-3 was associated with breast cancer risk only in part of Native Americann, with merely borderline significance (P = 0.06)." (PMID 37188722, 2023). "In a chemically-induced sarcoma model, an inverse relationship between IRF8 and MMP3 expression was demonstrated; in a mouse model of mammary cancer, loss of MMP3 reduced spontaneous lung metastasis." (PMID 36078039, 2022). "The importance of ECM proteins was clearly observed when overexpression of MMP3 in mice induced mammary carcinoma, despite having cancer-associated gene mutation." (PMID 36230849, 2022). "Our further interrogation using SCAN-B and METABRIC cohorts of breast cancer patients suggested that a high MMP3 expression score was associated with the better OS of patients (HR < 1, p = 0.0001)." (PMID 34072157, 2021). "In humans, increased tumor sc-IgGs were found to be associated with poor breast cancer patient outcomes and high levels of MMP3-/MMP12-cleaved IgG were detected in sera from inflammatory bowel diseases patients, who did not respond to anti-TNFα therapy." (PMID 32117299, 2020). "Specifically, MMP-3 has been associated with tumor initiation and progression, and the loss of MMP-3 was shown to suppress lung metastasis in an in vivo model of mammary carcinoma." (PMID 29390034, 2018). "Both MMP-9 and MMP-3 have been implicated to play a critical role in breast cancer invasion and metastasis in animal models and human patients." (PMID 25176506, 2014). "All three studies, however, found an association with lymph node positivity in patients with breast cancer, which we interpret as being consistent with our findings of a direct involvement of MMP-3 in tumor invasion promotion." (PMID 17922906, 2007). "MMP3 is associated with tumor growth and metastasis in breast cancer and CC." (PMID 37503314, 2023). "In this paper, we present a continuation of the evaluation of MMPs as new tumor markers for breast cancer, this time by assessing two metalloproteinases MMP-3 and MMP-7 as a diagnostic marker of early-stages breast cancer with Luminal A or Luminal B HER-negative subtypes." (PMID 37048701, 2023). "Furthermore, the -1171 5A allele as a high MMP-3 producer has been associated with the pathogenesis of various diseases like acute myocardial infarction, breast cancer, head and neck squamous cell carcinoma, and lung cancer." (PMID 33986628, 2021). "The overexpression of MMP-3 is associated with metastasis in ductal breast cancer patients." (PMID 33564686, 2021). "The results suggest that MMP-1 and MMP-3 might be associated with BC development, highlighting the need for further functional analysis of their role in breast cancer." (PMID 34445715, 2021). "In this regard, miR-21 was shown to target MMP-3 expression to regulate breast cancer invasion, and is found in breast malignancy with high proliferation, advanced-stage, and aggressive phenotypes, such as pregnancy-associated breast cancer." (PMID 34445715, 2021). "Additionally, rs650108 (10556C>T) is a sensitive SNP in MMP-3 that has been found to have an association with the risk of primary sclerosing cholangitis, breast cancer, and rotator cuff repair." (PMID 28445942, 2017). "Moreover, MMP3-loss reduced spontaneous lung metastasis in an orthotopic mouse model of mammary carcinoma." (PMID 26008967, 2015). "The MMP3 5A allele was associated with a poorer prognosis in breast cancer patients." (PMID 17958893, 2007). "Subsequently, we sought to verify the roles of ETS1 and MMP3 in dasatinib-mediated inhibition of breast cancer progression." (PMID 41462902, 2025). "For instance, MMP3 favors breast cancer progression while being a protective agent promoting leukocytes recruitment in skin carcinogenesis." (PMID 38740853, 2024).
breast cancer (continued). "In this study, MMP3 was significantly decreased in breast cancer brain metastasis, and the single-cell analysis showed that the breast cancer brain metastasis sample was enriched with macrophages." (PMID 39157383, 2024). "Prior research has highlighted GATA4’s capability to reduce MMP2 and MMP3 expression in breast cancer." (PMID 38653973, 2024). "For instance, MMP-3 is upregulated in breast cancer, and MMP-3 can induce EMT and promote malignant transformation in cultured cells." (PMID 39000490, 2024). "Quercetin and kaempferol, parent compounds, have been reported to impede breast cancer cell invasion notably by inhibiting MMP-3." (PMID 39062932, 2024). "Regarding breast cancer, MMP3 has been described to be over-expressed in neoplastic mammary tissue, to be involved in both mammary cancer invasion and metastasis, and has also been considered a prognostic factor." (PMID 38256245, 2024). "It is particularly interesting because we have previously shown that PRL-activated pTyr-PAK1 induces secretion of MMP-1 and MMP-3 in the breast cancer cells grown in 3D collagen IV." (PMID 38660565, 2024). "Focusing on CMN, according to the consulted literature, over-expression of MMP3 has been described in serum and tissue samples from bitches with mammary carcinoma." (PMID 38256245, 2024). "In vitro and in vivo study has demonstrated the involvement of MMP-3 in the metastasis of breast cancer cell line 4T1." (PMID 37048701, 2023). "MMP3 over-expression was correlated with tumor growth and metastasis in different types of cancer, including breast cancer." (PMID 37999477, 2023). "The active form of MMP-3 was reported to be overexpressed in breast cancer and found to catalyze E-cad proteolysis in that cancer." (PMID 37446087, 2023). "Given the suggested role of MMP-3 and MMP-7 in the pathogenesis of breast cancer and their diagnostic potential as demonstrated in research papers, we decided to test them as early tumor markers of breast cancer." (PMID 37048701, 2023). "Overexpression of MMP3 and its role as a prognostic factor have been reported in several cancers, including breast cancer." (PMID 37048701, 2023). "For example, PNU-74654 can inhibit the migration and invasion of breast cancer (BC) cells by upregulating E-cadherin and downregulating MMP3 and MMP9 to synergistically enhance the anticancer effect of fluorouracil (5-FU)." (PMID 37763649, 2023). "Recently, palbociclib treatment ameliorated the clinical symptoms and decreased serum levels of CRP and MMP-3 in patients with advanced breast cancer and RA." (PMID 34849618, 2022). "For instance, senescent fibroblasts promote branching morphogenesis in primary breast cancer organoids through their elevated secretion of matrix metalloproteinase-3 (MMP-3)." (PMID 36291792, 2022). "In some studies, MMP-3 has been reported to stimulate spontaneous tumor formation in the mammary glands of transgenic mice, suggesting its tumor-promoting role in breast cancer." (PMID 36741729, 2022). "We aimed to evaluate the contribution and association of single-nucleotide polymorphisms (SNPs) in MMP genes (MMP1, MMP2, MMP3, MMP7, MMP8, MMP9) with clinicopathological breast-cancer features." (PMID 36009438, 2022). "Sevoflurane has also been shown to increase the levels of MMP-3 and -9 in patients undergoing breast cancer surgery." (PMID 35223475, 2022). "Cluster 2 contained high levels of Mmp3, a matrix metalloproteinase expressed in senescent fibroblasts that has a possible role in breast cancer progression, which led us to label this population as “Mmp3hi HAFs”." (PMID 35439171, 2022). "MMP3 is reported to be upregulated in cancer, including breast cancer and is an EMT inducer in transgenic mice." (PMID 35646711, 2022).
breast cancer (continued). "Further analysis using breast cancer metastasis GSE110590 cohort showed that MMP3 was significantly altered in the bone, LN, and lung metastasis tissues compared to the primary tumor, with a propensity of reduced expression in LN and lung metastasis." (PMID 34072157, 2021). "To explore the mechanisms underlying the regulation of migration and invasion in breast cancer cells following sauchinone treatment, we first screened representative MMPs (MMP2, MMP3, MMP9, and MMP13) via immunoblotting analysis." (PMID 34643237, 2021). "Patients undergoing primary breast cancer surgery who received propofol/paravertebral anesthesia had less elevated MMP-3 and MMP-9 as compared with those who received sevoflurane based anesthesia during primary breast cancer surgery." (PMID 35127500, 2021). "For example, overexpression of STX2 can facilitate the carcinogenesis of mice breast cancer by increasing C/EBPβ, keratin-14, matrix metalloproteinase-3 (MMP-3), and β-catenin expression." (PMID 33754003, 2021). "The prognostic value of the MMP3 was also tested by Kaplan–Meier analysis of OS using the SCAN-B cohort of 3273 breast cancer patients and validated using the METABRIC cohort of 1904 breast cancer patients or TCGA-BRCA cohort of 1091 patients." (PMID 34072157, 2021). "Our results show higher immunohistochemical expression levels for MMP1 intensity and MMP-3 percentage and intensity for early-stage breast cancer (EI, EII)." (PMID 34445715, 2021). "Tumour cell MMP3 expression is a prognostic for poor survival in pancreatic, pulmonary and mammary carcinoma." (PMID 33683827, 2021). "MMP3 has also been investigated to over-express in the tumor cell of tissues, including breast cancer, lung cancer, and pancreatic colorectal 14, and indicate poor survival in those tumor types." (PMID 32922541, 2020). "Gene and protein expression of MMP‐3 was also analyzed in these cells as its expression is known to be upregulated during EMT in breast cancer." (PMID 31725949, 2020). "The present study supported that arctigenin suppressed breast cancer progression through the inhibition of GM-CSF, MMP-3, MMP-9, and TSLP." (PMID 32887217, 2020). "The downregulation of the expression of EMT transcription factors Snail‐1, Snail‐2, Twist‐1, Zeb‐1, and MMP‐3 in IL‐22−/−PyMT tumors suggests that IL‐22 mediates invasion through the EMT pathway in breast cancer." (PMID 31725949, 2020). "Thereby, MMP3 can cause EMT, oxidative DNA damage, genomic instability, and malignant transformation in cultured cells, and in genomically unstable mammary carcinomas in transgenic mice." (PMID 30621237, 2019). "Induction of an EMT program in breast cancer cells causes MMP production, and increased expression of MMP3, MMP10, and MMP13 was observed upon TGF-β stimulation of human breast cancer cell lines." (PMID 30356678, 2018). "The interaction information analysis revealed moderate effect between the markers -1607 1G/2G of MMP1, -1171 5A/6A of MMP3 and -1562 C/T of MMP9 genes which were conferring risk towards the progression of the breast cancer." (PMID 28961241, 2017). "We also demonstrate that osteoprotegerin knockdown represses Interleukin-1beta expression, Interleukin-1beta-mediated breast cancer cell invasion and MMP3 expression." (PMID 28143606, 2017). "Association of the MMP1–1607 1G>2G, MMP3-1171 5A>6A and MMP9-1562 C>T genotypes with breast cancer susceptibility and clinicopathological characteristics." (PMID 28961241, 2017). "The interaction dendrogram also further confirmed that MMP-1607 1G/2G and MMP3–1171 5A/6A SNPs have strong correlation whereas, MMP9-1562 C/T polymorphism has an additive effect on the risk of breast cancer development." (PMID 28961241, 2017). "Haplotype analysis of MMP1 and MMP3 genes present on chromosome 11q was performed to calculate the combined effect of MMP1–1607 1G/2G and MMP3–1171 5A/6A polymorphisms on breast cancer." (PMID 28961241, 2017).